KRAS (KRas proto-oncogene, GTPase)
Diseases named in the same sentence as KRAS in open-access papers (continued):
Sharing a sentence is not in itself a finding about the gene and the disease.
intestinal tumors (15 papers, 2008 to 2022). "In mice, presence of a KRAS mutation in an APC mutant background was also associated with reduced survival due to accelerated growth of intestinal tumors." (PMID 27729614, 2016). "Third, murine and human intestinal tumors with KRAS mutations are mostly MSI-stable or MSI-low, whereas BRAF mutant human tumors are frequently MSI-high." (PMID 23845441, 2013). "Next, in order to understand whether the development of KRAS-mutated mouse intestinal tumors is associated with increased neutrophils, we examined the number of neutrophils in peripheral blood, spleen, BM and mLN of APC-WT and APC-KRASG12D mice at different time points." (PMID 32228650, 2020). "Our results are in contrast with previous reports showing that oncogenic KRAS signaling stimulates Wnt pathway, which in turn promotes intestinal tumor growth and invasion." (PMID 34108518, 2021). "Focusing on a genetically engineered mouse model, cultured spheres derived from APC/KRAS/PTEN intestinal tumours were largely insensitive to BEZ235 as a single agent; however, they responded to sequential treatment with bortezomib followed by BEZ235." (PMID 27897178, 2016). "In view of the established role of Wnt in regulating stemness, we attempted the isolation of cancer stem cells (CSCs) from Apc- and Apc/KRAS-mutant intestinal tumours." (PMID 24069241, 2013). "Furthermore, it was shown that the expression of the intestinal stem cell markers CD44, CD133 and CD166 was induced in intestinal tumors only of bouble mutant APC defective/KRAS-mutant mice, thus indicating that APC mutation is required for CSC activation by oncogenic mutant KRAS." (PMID 29652830, 2018). "In contrast with these studies, our data show that inhibition of CRC cells does not modify ERK content and phosphorylation, thus supporting the conclusion that EIF5A function is not coupled to KRas expression and activity in intestinal tumors." (PMID 33303756, 2020). "Interestingly, only the combination of KRAS activation and TGFBR2 inactivation in mice have been found to induce formation of intestinal neoplasms." (PMID 28426742, 2017).
large cell carcinoma (15 papers, 2009 to 2026). A malignant epithelial neoplasm composed of large, atypical cells. "There were three (15.8%) EGFR mutations and four (21.1%) KRAS mutations in large cell carcinoma." (PMID 26486077, 2015). "Large cell carcinoma line NCI-H460 had both KRAS and PIK3CA mutations." (PMID 19238210, 2009). "The PD-L1-high group contained two EGFR-mutant and five KRAS-mutant cell lines, the histological characteristics of which resulted six of them being classified as adenocarcinomas and one as a large cell carcinoma, while the PD-L1-low group contained only two KRAS-mutant adenocarcinoma cell lines." (PMID 27846317, 2016). "Lysates from eight EGFR-mutant, four KRAS-mutant, and two EGFR/KRAS wild-type LUAD, as well as two large cell carcinoma and four SCLC cell lines were assessed." (PMID 34121659, 2021). "KRAS mutations were exclusively found in ADC (3/20, 15%) and large cell carcinoma (LC, 2/3, 67%) but not in SQCC." (PMID 27105513, 2016). "In addition, knockdown of KRAS resulted in downregulation of lamin pS392 in adenocarcinoma A549 and H322 cells but not in large cell carcinoma H1299 cells." (PMID 21637843, 2011). "Focal NED and amphicrine tumours exhibited cellular subpopulations enriched for KRAS, IL2-STAT5 and TNF signalling pathways, absent in small- and large-cell carcinomas, which were instead enriched for Myc and E2F pathways." (PMID 40705968, 2025).
pancreatic neuroendocrine tumor (15 papers, 2003 to 2026). Pancreatic endocrine tumor, also known as pancreatic neuroendocrine tumor (PNET), describes a group of endocrine tumors originating in the pancreas that are usually indolent and benign, but may have the potential to be malignant. "The human pancreatic NET cell line BON1 harbors a mutation in NRAS, while the human pancreatic NET cell line QGP-1 harbors a mutation in KRAS." (PMID 33807122, 2021). "In this study, we report the first KRAS-initiated pancreatic neoplasia model that closely recapitulates pancreatic endocrine tumors." (PMID 31231585, 2019). "In summary, we successfully developed a novel system combining CRE/Lox technology to establish oncogenic KRAS-initiated pancreatic endocrine tumors." (PMID 31231585, 2019). "However, the human pancreatic neuroendocrine tumor cell line BON1 harbors a mutation in NRAS, while the human pancreatic neuroendocrine tumor cell line QGP-1 harbors a mutation in KRAS." (PMID 33807122, 2021). "In contrast, no KRAS mutation was detected in tumors in a patient with a pancreatic neuroendocrine tumor." (PMID 32704002, 2020). "Importantly, KRAS has been shown to not possess oncogenic functions in pancreatic endocrine cells and activating KRAS mutations were never found in islet cell tumors 21,37." (PMID 36289205, 2022). "In a study of 21 pancreatic NET G3, neither abnormal pRb expression nor KRAS mutations were found." (PMID 34647903, 2021).
rhabdomyosarcoma (15 papers, 2012 to 2025). A rare aggressive malignant mesenchymal neoplasm arising from skeletal muscle. "Among these, the onset of rhabdomyosarcoma in patients with EN harbouring somatic mutations in KRAS has been described." (PMID 37636262, 2023). "Collectively, this suggests that YAP and KRAS together both regulate the rhabdomyosarcoma core gene expression programme, which are genes associated with sustained proliferation whilst blocking terminal differentiation." (PMID 30353028, 2018). "In contrast, there is no overlap between genes that are repressed in both YAP1 S127A and KRAS G12V-Cdkn2a null-induced rhabdomyosarcoma, and genes that are significantly mutated in cancer." (PMID 30353028, 2018). "Dysregulated KRAS signaling has also been implicated in rhabdomyosarcoma and Ewing's sarcoma pathogenesis." (PMID 28969007, 2017). "The first KRAS G12D mutation was reported in an infant with epidermal nevus, polycystic kidneys and rhabdomyosarcoma." (PMID 26521233, 2015). "To date, five patients carrying somatic mutation in codon 35 of KRAS and codon 13 of HRAS with extensive EN and rhabdomyosarcoma have been reported." (PMID 37636262, 2023). "In a model of RAS-driven rhabdomyosarcoma tumorigenesis, expression of KRAS under the CDH15 promoter resulted in less differentiated and more aggressive tumors." (PMID 31941033, 2020). "This revealed that only 20% of the up or downregulated genes are identical, suggesting substantial differences in gene expression between YAP and KRAS-driven rhabdomyosarcomas." (PMID 30353028, 2018). "Only 2 (CBEP3 and SATB1) out of 100 genes that are down regulated in YAP1 S127A and KRAS G12V-Cdkn2a-null induced rhabdomyosarcoma overlap with the bottom 100 genes whose low expression is best associated with poor survival in 18,000 cases of human cancer." (PMID 30353028, 2018). "Dr. Chang described eight patients with KRAS mutant mosaicism and their clinical features, which in several cases included embryonal tumors (rhabdomyosarcoma and Wilms tumor) and other less common symptoms, such as epilepsy, polycystic kidneys, T‐cell deficiency, and multifocal lytic bone lesions." (PMID 35266292, 2022). "This mosaic KRAS G12D mutation was detected in both the epidermal component of the nevus and in the rhabdomyosarcoma, but not in the unaffected tissues or normal skin or blood." (PMID 34208656, 2021). "KRAS is involved both in angiosarcomas and rhabdomyosarcomas." (PMID 34359782, 2021). "In addition, expression of KRAS G12V and knockout of p16 in isolated satellite cells results in the formation of rhabdomyosarcoma with pleomorphic features." (PMID 30353028, 2018). "The two main subtypes are alveolar rhabdomyosarcoma (ARMS), which is associated with PAX3/7-FOXO1 fusion genes, and embryonal rhabdomyosarcoma (ERMS), which is associated with mutations in common cancer genes such as HRAS, KRAS, NRAS, CTNNB1, PIK3CA and TP531." (PMID 30353028, 2018). "Our main finding is that YAP1 S127A and KRAS G12V-Cdkn2a-driven rhabdomyosarcomas only share 20% of the up or down-regulated genes and that the expression of KRAS G12V together with various genetic manipulations of myoblasts does not activate Yap in these cells." (PMID 30353028, 2018). "This mosaic KRAS G12D mutation was detected in both the epidermal component of the EN and in the rhabdomyosarcoma, but not in the unaffected tissues or normal skin or blood." (PMID 26521233, 2015). "Notably, KRAS is expressed in angiosarcoma and rhabdomyosarcoma as well." (PMID 34359782, 2021). "Among the rhabdomyosarcomas, alterations in FGFR1, KRAS, and MYC were detected." (PMID 37726478, 2023).
Costello syndrome (14 papers, 2010 to 2025). "Among this group of disorders, craniosynostosis appears to be consistently associated with Noonan, CFC, and Costello syndromes with pathogenic variants most frequently reported in BRAF, HRAS, KRAS, and PTPN11." (PMID 37774117, 2024).
endometrial tumors (14 papers, 2010 to 2025). "Several studies have shown that PIK3R1 frequently coexists with PTEN and KRAS mutations in endometrial tumors." (PMID 39858051, 2025). "Somatic mutations in PIK3CA and KRAS frequently co-occurred in colorectal, lung, head and neck, gastric and endometrial tumors." (PMID 32087721, 2020). "Mutation co-occurrence occurred frequently with PIK3CA and KRAS genes in lung, colorectal, head and neck, gastric and endometrial tumors." (PMID 32087721, 2020). "G13D of KRAS, presented in both CC groups with the signature of mismatch repair deficiency, is reported to be associated with mismatch repair deficiency signatures in gastric and endometrial tumours." (PMID 36936374, 2023). "The CHEK1 mRNA expression level was elevated in both groups of endometrial tumors compared to KRAS and ATR mRNA expression levels." (PMID 38669256, 2024). "Molecular characterization of endometrial tumors has demonstrated that PIK3CA mutations, PTEN loss, and PI3K and KRAS activation are key events in carcinogenesis." (PMID 32754300, 2020). "In addition, tumor miRNA expression appears to be associated with patient age, lymphovascular invasion and the KRAS-variant, supporting the hypothesis that altered tumor biology can be measured by miRNA expression, and that the KRAS-variant likely impacts endometrial tumor biology." (PMID 24732316, 2014). "Based on our understanding of receptor tyrosine kinase-MAPK signaling, and our preliminary analysis of 115 endometrial tumors, we anticipated that FGFR2 and KRAS mutations would occur in a mutually exclusive pattern." (PMID 22383975, 2012). "In endometrial tumors that deeply invaded the myometrium, a 3-fold increase in the KRAS protein level was observed, along with a slightly higher pATR expression (2.1-fold), while the number of pCHEK1 positive cells did not depend on the depth of tumor invasion into the myometrium." (PMID 38669256, 2024). "Similarly, in endometrial tumors, KRAS G13D mutated tumors showed a higher prevalence of NF1 and PTEN alterations compared to KRAS G12D (NF1: 14.0% vs. 6.1%, FDR p = 0.005; PTEN: 70.6% vs. 55.1%, p = 0.0006, respectively)." (PMID 36494601, 2022). "Of particular interest are the findings that concomitant KRAS-activation and PTEN-loss induced progesterone-resistance and loss of stromal PR in endometrial tumors, but that progesterone sensitivity could be reintroduced through exogenous administration of PR into the stroma." (PMID 31827798, 2019).
esophageal squamous cell carcinoma (14 papers, 2013 to 2025). Esophageal squamous cell carcinoma (ESCC) is a type of esophageal carcinoma (EC) that can affect any part of the esophagus, but is usually located in the upper or middle third. "miR-27a inhibited A549 cell proliferation via MET signaling and in esophageal squamous cell carcinoma functioned as a tumor suppressor through binding to oncogene KRAS." (PMID 32039029, 2019). "It is reported that STK11-activated autophagy enhances resistance to the combination of trametinib and radiation in KRAS-mutant NSCLC and promotes esophageal squamous cell carcinoma cell survival after radiation." (PMID 34434896, 2021).
fibrosarcoma (14 papers, 2009 to 2025). A malignant mesenchymal fibroblastic neoplasm affecting the soft tissue and bone. "Constitutively active KRAS protein stimulates rapidly accelerated fibrosarcoma kinases, setting off a cascade that culminates in the activation of extracellular signal-regulated kinase." (PMID 40527836, 2025). "One of the prominent downstream signaling pathways activated by KRAS is the rapidly accelerated fibrosarcoma-mitogen-activated protein kinase kinase-extracellular signal-regulated kinase pathway." (PMID 40527836, 2025). "Kirsten rat sarcoma viral oncogene homolog (KRAS) upregulates RTA expression through the rapidly-accelerated fibrosarcoma (RAF)/mitogen-activated protein kinase (MEK)/ERK pathway." (PMID 32957532, 2020).
myelodysplastic syndrome (14 papers, 2010 to 2025). A clonal hematopoietic disorder characterized by dysplasia and ineffective hematopoiesis in one or more of the hematopoietic cell lines. "Along these lines, recent work evaluating the role of gene mutations on the prognosis of myelodysplastic syndromes demonstrated that patients with mutations in KRAS or NF1 show worse OS than patients with NRAS or CBL mutations." (PMID 29259247, 2017). "Notably, in one of these patients chronic MPN transformed into a secondary myelodysplastic syndrome harboring a dominant KRAS mutated clone." (PMID 40623967, 2025). "After that, in 1994, cancer-specific DNA mutations in NRAS (myelodysplastic syndrome (MDS)) and KRAS (pancreatic cancer) were found in the blood of cancer patients." (PMID 27128908, 2016). "Significantly, RAS mutations, usually in KRAS and NRAS, are also frequent events in myeloid malignancies, and have been detected in 3% to 40% of myelodysplastic syndrome (MDS) and AML." (PMID 29029494, 2017). "Activating mutations in either NRAS or KRAS genes occur in AML, juvenile myelomonocytic leukaemia (JMML), chronic myelomonocytic leukaemia (CMML), childhood ALL and myelodysplastic syndromes (MDS)." (PMID 29940987, 2018).
oral squamous cell carcinoma (14 papers, 2011 to 2025). "A recent supportive study on Oral Squamous Cell Carcinoma (OSCC) postulated that increased KRAS levels were linked to poorly differentiated tumors, more advanced pathological stages, and lymph invasion, suggesting the crucial role of KRAS in triggering both local and distant metastasis in OSCC37." (PMID 40913040, 2025). "The low KRAS mutation frequency in the present study is in agreement with previous small-scale studies of HNSCC that reported a mutation frequency of 2.4% (1/42 samples) in oral squamous cell carcinoma, 4.5% (1/22 samples) in oropharyngeal cancer and 0% (0/16 samples) in HNSCC." (PMID 22994622, 2012). "In addition, SCH772984 plus apatinib has been effective against oral squamous cell carcinoma (OSCC), and SCH772984 is also an alternative for the treatment of LKB1 and LKB1/KRAS-mutated NSCLC." (PMID 37976123, 2023). "KRAS has been shown to be a direct miR-181a target in oral squamous cell carcinoma." (PMID 27517749, 2016). "Recently, KRAS was shown to be a direct miR-181a target in oral squamous cell carcinoma." (PMID 27517749, 2016). "MiR-181a was found down-regulated in oral squamous cell carcinoma (OSCC) and was demonstrated to target the 3′-UTR of KRAS mRNA." (PMID 26646588, 2016). "Low expression of miR-126-5p in oral squamous cell carcinoma has also been observed by others, with evidence of negative regulation of tumorigenesis via targeting of KRAS, as well as migration and invasion of cancer cells via downregulation of ADAM9." (PMID 34439138, 2021).
ovarian clear cell cancer (14 papers, 2013 to 2025). An invasive malignant neoplasm that arises from the ovary and is characterized by a predominance of clear and hobnail malignant epithelial cells. "Then, the researchers detected PI3CA and KRAS mutations in cfDNA from ovarian clear cell carcinoma using ddPCR and found that patients with higher levels of PIK3CA-H1047 R and KRAS-G12D had shorter PFS." (PMID 33936202, 2021). "On the other hand, our recent studies clarified that cancer-associated genes such as ARID1A, PIK3CA and KRAS are frequently mutated not only in ovarian clear cell carcinoma but also in ovarian endometriosis." (PMID 32868822, 2020). "ARID1A, PIK3CA, CTNNB1, PTEN, and KRAS are commonly mutated in both endometrioid and clear cell ovarian cancers from women." (PMID 30087267, 2018). "Recent whole genome or targeted sequencing studies have identified frequent mutations of ARID1A and PIK3CA genes, and moderate mutations of PPP2R1A and KRAS in ovarian clear cell carcinomas, mutations of PTEN, CTNNB1 and KRAS in endometrioid cancer." (PMID 23466883, 2013). "For the study of genetically engineered mouse models, fortunately, both endometrioid and clear cell ovarian cancer have high frequency mutations in only a handful of genes: ARID1A, PIK3CA, CTNNB1, PTEN, and KRAS." (PMID 30087267, 2018). "Previous studies showed that the somatic mutations of ovarian clear cell carcinoma (mainly in ARID1A, PIK3CA, KRAS and PPP2R1A) might be related to chromatin remodeling, cell proliferation, cell cycle checkpointing and cytoskeletal organization." (PMID 34680501, 2021). "However, KRAS p.G12V was also described recently in ovarian clear cell carcinoma via whole exome sequencing, though this subtype is mainly characterized by frequent activating mutations in PIK3CA and infrequent mutations in KRAS." (PMID 31197119, 2019). "Notably, recent genome sequencing studies reported frequent mutations of ARID1A and PIK3CA genes and moderate mutations of PPP2R1A and KRAS in ovarian clear-cell carcinomas and frequent mutations of PTEN, CTNNB1, and KRAS in endometrioid cancer." (PMID 26413541, 2015). "Interestingly, KRAS G12C was observed in 0.6% patients overall, and in 5.7% of sarcomatoid carcinoma of the lung and 5.4% of clear cell ovarian cancer tumors, but none in small-bowel cancer tumors." (PMID 35359599, 2022).
renal carcinoma (14 papers, 2008 to 2025). A carcinoma arising from the epithelium of the renal parenchyma or the renal pelvis. "SLC4A4 overexpression restrained cell proliferation and metastasis by suppressing Kirsten rat sarcoma viral oncogene (KRAS) expression in renal cancer cells." (PMID 30668544, 2019). "Given that miR-223-3p suppressed the SLC4A4/KRAS axis, miR-223-3p gene therapy could be an effective treatment for renal cancer." (PMID 30668544, 2019). "As another member of the JADE family JADE1 has been linked to renal cancer pathogenesis through a VHL-mutation-dependent mechanism, we next sought to determine if JADE2 mRNA was also associated with mutation of key oncogenic driver mutations in NSCLC such as KRAS or ALK." (PMID 37761019, 2023). "We went on to examine the correlation of KRAS and NAP1L1 with miR-532-5p in 20 renal cancer tissues." (PMID 30082686, 2018).